CBR3 (carbonyl reductase 3)
Description:
Catalyzes the NADPH-dependent reduction of carbonyl compounds to their corresponding alcohols. Has low NADPH-dependent oxidoreductase activity. Acts on several orthoquinones, acts as well on non-quinone compounds, such as isatin or on the anticancer drug oracin. Best substrates for CBR3 is 1,2-naphthoquinone, hence could play a role in protection against cytotoxicity of exogenous quinones. Exerts activity toward ortho-quinones but not paraquinones. No endogenous substrate for CBR3 except isatin has been identified.
Synonyms: SDR21C2; HEL-S-25; hCBR3
Tractability: Small molecule: a structure with a bound ligand is known; it has a binding pocket of medium quality. PROTAC: ubiquitination databases record sites on it; its protein half-life has been measured.
Target class: Enzyme; Oxidoreductase
Safety:
Unwanted effects reported when the protein is acted on. In parentheses: how it was acted on, where the effect was seen, and who reports it.
cardiac damage (source: ClinPGx)
cardiac damage after anthracycline exposure (source: ClinPGx)
less tumor reduction (source: ClinPGx)
metabolism of doxorubicin (source: ClinPGx)
neutropenia (source: ClinPGx)
tumor reduction (source: ClinPGx)
Gene: Protein-coding gene on chromosome 21 (36,135,079 to 36,146,566, forward strand). Ensembl gene ENSG00000159231.
Subcellular location: Cytoplasm
Subcellular location (Human Protein Atlas): Cytosol; Nucleoplasm
Pathways (Reactome):
Metabolism: Phase I - Functionalization of compounds
Gene Ontology:
Molecular function: carbonyl reductase (NADPH) activity; NADPH binding; NADPH dehydrogenase (quinone) activity; protein binding; 3-beta-hydroxysteroid 3-dehydrogenase (NADP+) activity; alcohol dehydrogenase (NADP+) activity; oxidoreductase activity, acting on NAD(P)H, quinone or similar compound as acceptor; oxidoreductase activity, acting on the CH-OH group of donors, NAD or NADP as acceptor
Biological process: cognition; xenobiotic metabolic process; phylloquinone catabolic process
Cellular component: cytoplasm; cytosol; extracellular region
Genetic constraint (gnomAD): Loss-of-function variants: 13 observed, 10.26 expected, observed/expected ratio (o/e) 1.27, 90% interval 0.82 to 1.85. The upper end of that interval is the gene's LOEUF score, 1.85, which puts it in group 6 of 6, group 1 being the genes least tolerant of losing a copy. Missense variants: 265 observed, 313.29 expected, observed/expected ratio (o/e) 0.85, 90% interval 0.76 to 0.94. Synonymous variants: 112 observed, 129.83 expected, observed/expected ratio (o/e) 0.86, 90% interval 0.74 to 1.01.
Homologues: Orthologues: chimpanzee CBR3 (99% identical), macaque CBR1 (92% identical), dog CBR3 (87% identical), mouse Cbr3 (85% identical), pig CBR3 (85% identical), rabbit CBR3 (85% identical), rat Cbr3 (85% identical), guinea pig CBR3 (81% identical), zebrafish cbr1l (53% identical), Drosophila melanogaster CG13377 (21% identical), zebrafish zgc:112146 (21% identical), zebrafish zgc:92161 (21% identical), and 23 more. Paralogues in human: CBR1 (72% identical), DHRS4 (22% identical), HSDL2 (22% identical), DHRS1 (21% identical), DHRS2 (21% identical), DHRS11 (20% identical), DHRS7 (19% identical), DHRS7B (19% identical), DHRS4L2 (18% identical), DHRS7C (18% identical), HSD11B1L (18% identical), RDH8 (17% identical), and 1 more.
Diseases named in the same sentence as CBR3 in open-access papers:
CBR3 is named in the same sentence as 32 diseases in open-access papers, as found by Europe PMC text mining. Sharing a sentence is not in itself a finding about the gene and the disease. The quoted sentences say what the papers report.
breast carcinoma (7 papers, 2015 to 2025). "The researchers strongly agreed that their study repeatedly showed that the CBR3 gene rs1056892 has a significant association with CHF (p = 0.004) in breast cancer patients." (PMID 40362292, 2025). "In 92 breast cancer patients genotyped for the CBR3 gene, those with the CBR3 V244M variant had a significant reduction of LVEF six months after the initiation of doxorubicin, although the numerical reduction of LVEF was small." (PMID 36230587, 2022). "CBR3 Val244Met (rs1056892) polymorphism can also affect the risk of anthracyclines induced cardiomyopathy in child cancer survivors and adult breast cancer patients." (PMID 36312261, 2022). "The CBR3 Val244Met polymorphism was also associated with cardiotoxicity in breast cancer patients treated with trastuzumab." (PMID 36312261, 2022). "We performed a prospective pharmacogenetic study to analyze the impact of the functional CBR3 V244M polymorphism on the development of acute anthracycline cardiotoxicity in a cohort of 92 breast cancer patients receiving DOX." (PMID 33975650, 2021). "This study evaluated the presence of associations between CBR3 V244M genotype status and changes in echocardiographic parameters in breast cancer patients undergoing doxorubicin treatment." (PMID 33975650, 2021). "The presence of the variant carbonyl reductase 3 (CBR3) appeared as a double-edged sword in a study of Asian breast cancer patients." (PMID 26203310, 2015). "Secondly, we observed the association of CBR3 (Carbonyl-reductase 3) V244M, a polymorphism that has previously been associated with anthracycline-induced heart failure in childhood cancer patients and in patients with breast cancer." (PMID 37305569, 2023). "CBR3 V244M genotype status is associated with changes in echocardiographic parameters suggestive of early anthracycline-related cardiomyopathy in subjects undergoing chemotherapy for breast cancer." (PMID 33975650, 2021). "Furthermore, another CBR3 variant (11 G > A) has been shown to influence the relative expression of CBR3—and subsequent doxorubicinol formation—in a cohort of Southeast Asian breast cancer patients." (PMID 33574985, 2021). "Interestingly, a cross-sectional observational study of anthracycline-induced cardiomyopathy in a cohort of women with breast cancer found the CBR3 V244M AA genotype more often in patients with systolic dysfunction than in cases with normal LVEF > 55%." (PMID 33975650, 2021).
cardiomyopathy (4 papers, 2021 to 2025). A disease of the heart muscle or myocardium proper. "Our prior work with the Children’s Oncology Group identified a single nucleotide polymorphic variant in the CBR3 gene (rs1056892, CBR3 V244M) associated with the risk of anthracycline-related cardiomyopathy in survivors of childhood cancers." (PMID 33975650, 2021). "CELF4 was first associated with anthracycline-induced cardiomyopathy in a GWAS study of childhood cancer survivors by the same group that first identified CBR3." (PMID 34575190, 2021). "The CBR3 V244M single nucleotide polymorphism has been linked to the risk of anthracycline-related cardiomyopathy in survivors of childhood cancer." (PMID 33975650, 2021). "The homozygous CBR3 G genotype (CBR3 V244) was found to correlate with a 3.3-fold increased risk of cardiomyopathy following exposure to anthracyclines (1–250 mg/m2) compared with CBR3 GA/AA genotypes." (PMID 33975650, 2021). "For both CBR3-rs1056892 and CBR1-rs9024 variants, carrying the GG genotype along with receiving low-to-moderate doses of anthracycline increased the risk of cardiomyopathy by 3.6-fold compared to AA and GA genotypes." (PMID 40413218, 2025). "Hence, in this case the CBR3 V244M polymorphism does not at all explain the reported increased risk of anthracycline-induced cardiomyopathy in African American patients relative to other populations, as the allele associated with cardiomyopathy is less common in African Americans." (PMID 34575190, 2021).
heart failure (2 papers, 2021 to 2023). Inability of the heart to pump blood at an adequate rate to meet tissue metabolic requirements. "Two loci, TRPC6 and CBR3, were associated with cardiac events in the NSABP B-31 patients and analyses suggest that both associations are the effects of chemotherapy rather than trastuzumab and further extend the evidence for both as putative risk genes for doxorubicin-induced heart failure." (PMID 37305569, 2023).
oral squamous cell carcinomas (2 papers, 2008 to 2019). "At present, CBR3 has become potential biomarkers in uterine leiomyomas disease, type 2 diabetes, oral squamous cell carcinomas, and BC." (PMID 31285391, 2019). "Our results suggest that the cytostatic effects of RA could be mediated by the activation of endogenous CBR3 gene in oral squamous cell carcinomas (OSCCs), and the expression is a potential marker for oral malignancy." (PMID 19088887, 2008).
prostate carcinoma (2 papers, 2019 to 2021). A carcinoma that arises from epithelial cells of the prostate gland. "PlncRNA1, also called CBR3AS1, located in the antisense region of carbonyl reductase 3 (CBR3), was first found to be upregulated in prostate cancer." (PMID 34820453, 2021). "PlncRNA-1 prostate cancer-up-regulated long noncoding RNA 1, (also known as CBR3-AS1), located in the antisense region of carbonyl reductase 3 (CBR3), is overexpressed in cell lines and tissues of prostate cancer (CaP)." (PMID 31336999, 2019).
type 2 diabetes (2 papers, 2013 to 2019). "A recent clinical study showed that a genetic variation in Cbr3 gene in humans correlates with type 2 diabetes and this effect can potentially be attributed to the catalysis of the conversion of prostaglandin E2 to prostaglandin F2α." (PMID 23710285, 2013).
colon cancer (1 paper, 2022). "Particularly, AURKA, which is associated to colon cancer and was recently found to be over expressed also in hematological malignancies, as well as the drug resistant associated genes ABCB1, XRCC1 and CBR3 turned out to be affected." (PMID 35836575, 2022).
Crohn disease (1 paper, 2023). A gastrointestinal disorder characterized by chronic inflammation involving all layers of the intestinal wall, noncaseating granulomas affecting the intestinal wall and regional lymph nodes, and transmural fibrosis. "Our findings suggest that CBR3 may be involved in the pathogenesis of pediatric Crohn’s disease." (PMID 36936436, 2023).
frontotemporal lobar degeneration (1 paper, 2012). "The CBR3 protein, which catalyzes reduction of carbonyl compounds to their corresponding alcohols, has been found to be differentially expressed in the cerebellum of patients with atypical cases of frontotemporal lobar degeneration with fused in sarcoma-positive inclusions compared to controls." (PMID 23227193, 2012).
cancer (11 papers, 2008 to 2025). A tumor composed of atypical neoplastic, often pleomorphic cells that invade other tissues. "We previously demonstrated an association of the CBR3 V244M polymorphism with a late manifestation of cardiac dysfunction in long term survivors of pediatric cancers." (PMID 33975650, 2021). "Asn555-p85β, equivalent to Asn564-p85α (mutated to lysine or aspartic acid in cancers), interacts with the largely disordered CBR3 (Cβ5/Cβ6 loop)." (PMID 21362552, 2011). "Previous studies have shown that CBR3 is involved in the metabolism of xenobiotics, such as drugs and environmental toxins, and its expression is upregulated in various cancer types." (PMID 36936436, 2023). "Upregulation of carbonyl reductase 3 has also been reported in human cancer cells in response to oxidative stress (Ebert, Kisiela, Malátková, El‐Hawari, & Maser, 2010)." (PMID 33144962, 2020). "Keap1-knockdown and then Nrf2 activation resulted in dramatic induction of human CBR3 in cancer cell lines." (PMID 22808024, 2012). "Our results demonstrate that the expression of CBR3 mRNA was significantly reduced in OSCCs, especially in highly invasive cancers compared with pre-malignant dysplasias and hyperplasias." (PMID 19088887, 2008). "Additional genetic analyses are needed in large prospective cohorts of adult cancer patients treated with anthracyclines and followed for extended periods of time to further investigate the role of CBR3 V244M across patients of different ages, cancer types, and treatment regimes." (PMID 33975650, 2021). "CBR3 mRNA expression could regulate human cancer cell lines by the Nrf2 pathway." (PMID 31285391, 2019). "The CCLE database analysis demonstrated that the two hub gene expression level of CBR3 and RHPN1 ranked higher in a variety of cancer cell line." (PMID 31285391, 2019). "The three central genes, CBR3, SF3B6, and RHPN1, might play important roles in malignancy cancer transformation." (PMID 34876005, 2021).
tumor (4 papers, 2010 to 2022). "The 11G>A variant (rs8133052) in CBR3 has been shown to influence tumor tissue expression of CBR3 and is associated with inter-individual variability in clinical outcomes." (PMID 21037853, 2010). "As for PCA clusters, high Pearson correlation coefficients of gene expression within the cluster were only in case of AKR1C3, CBR1, CBR3 genes (r = 0.64 − 0.77, p-value < 0.05) in LUSC tumor as well as CBR1 and CBR3 (r = 0.72 − 0.86, p-value < 0.05) in ESCA tumor." (PMID 35453789, 2022). "Most of the transcriptomic signatures (without subgroup analysis) still show acceptable tumor specificity with the exception of the signature containing PTGDS, CBR3, PTGIR, PTGFR, PTGDR2, and PTGER3 genes in HNSC tumor, which is similar to other tumors (BRCA, CESC, LUAD, SARC, and UCES)." (PMID 35453789, 2022).
gastrointestinal disease (1 paper, 2024). A disease that occurs in the gastrointestinal system, excluding the hepatobiliary system. "Cyp2b10 and Cyp2b19 are members of the CYP450 enzyme family, in T2DM-induced gastrointestinal diseases, Cbr3 negatively regulates the expression of Cyp2b10 and Cyp2b19 proteins, resulting in elevated protein expression." (PMID 39211388, 2024).
CBR3 also shares sentences with these, for which no sentence is quoted: childhood cancer (4 papers); acute lymphoblastic leukemia (2); congestive heart failure (2); infection (2); amyotrophic lateral sclerosis (1); breast tumor (1); cardiac diseases (1); cardiovascular diseases (1); cholestasis (1); diabetic (1); end-stage renal disease (1); gastroenteropathy (1); hematological malignancies (1); injury (1); ischemic heart disease (1); leukoplakia (1); metastatic melanoma (1); migraine (1); renal fibrosis (1); sarcoma (1).